AR (androgen receptor)
Diseases named in the same sentence as AR in open-access papers (continued):
Sharing a sentence is not in itself a finding about the gene and the disease.
cryptorchidism (30 papers, 2009 to 2025). The failure of one or both testes of a male fetus to descend from the abdomen into the scrotum during the late part of pregnancy. "It is implicated in the early prenatal development, enhances androgen receptor transactivation, and has been related to Sotos syndrome, presenting mostly with growth and neurological abnormalities, but sometimes also with cryptorchidism and malignant tumors." (PMID 31500094, 2019). "The present data further indicate that AR is expressed in the gubernaculum during a time frame that overlaps with susceptibility of the rat fetus to antiandrogen-induced cryptorchidism." (PMID 30568634, 2018). "Interestingly, the association between TC and cryptorchidism has been documented in DSD from both AR mutation and PMDS." (PMID 31338064, 2019). "Mutations in androgen receptor (AR) gene are a frequent cause of cryptorchidism development." (PMID 30093884, 2018). "Developmental differences in cell-specific AR expression in LE/orl fetal gubernacula may contribute to the dysmorphism and aberrant function that underlies cryptorchidism susceptibility in this strain." (PMID 30568634, 2018). "In addition to this result of our study there is another study which shows a probable contribution of GGN 24 allele to AR dysfunction, which is in correlation with cryptorchidism and spermatogenic failure." (PMID 26221130, 2015). "Our genetic and genomic studies of the LE/orl rat, a model of inherited cryptorchidism, suggest that dysfunctional AR signaling contributes to failure of testicular descent in this strain." (PMID 30568634, 2018). "This study reports a novel familial variant in the AR gene, underscoring the importance of genetic evaluation in newborns presenting with cryptorchidism, with or without associated systemic manifestations." (PMID 41142184, 2025). "Furthermore, polymorphisms in the androgen receptor (AR), TGFBR3, and Hoxa11 genes and in genetic loci coding for cytoskeleton-associated proteins have been recognized as contributing risk factors for cryptorchidism." (PMID 31936283, 2020). "Testosterone and the androgen receptor (AR) are related to cryptorchidism." (PMID 32098036, 2020). "Knockout experiments in mice clearly show independent requirements for INSL3/RXFP2 and androgens in testicular descent; nevertheless causative mutations in INSL3, RXFP2, AR (androgen receptor) or the Leydig cell regulator NR5A1 (steroidogenic factor-1), are rare in cases of cryptorchidism." (PMID 30083133, 2018). "For cryptorchidism, both the androgen receptor and gonadotropin-releasing hormone 1 were predicted." (PMID 21846611, 2011). "In the same way, in vivo KCTD13-null mice exhibited reduced nuclear AR levels, decreased expression of SOX9, smaller testis, cryptorchidism, micropenis, and subfertility." (PMID 41595460, 2025). "Thus, we quantitatively analyzed the mRNA levels of AR and LHR in gubernacular cells derived from the control patient (i.e., the patient affected by cryptorchidism) and patients #4 and #15." (PMID 35159259, 2022). "Studies of androgen receptor knockout (ARKO) and tfm (testicular feminization) male mice, androgen-exposed female mice, and anti-androgen-exposed rats clearly show that the CSL is regulated by androgens and that its persistence leads to cryptorchidism." (PMID 30083133, 2018).
sarcopenia (30 papers, 2009 to 2026). Progressive decline in muscle mass due to aging which results in decreased functional capacity of muscles. "As 11KT is a potent androgen receptor agonist, 11-oxygenated androgen deficiency may potentially contribute to the development of sarcopenia, frailty, and overall mortality particularly in female patients with CKD." (PMID 39382395, 2025). "Taken together, our results suggest that oxidative stress, typical of age-related disorders, such as sarcopenia and frailty, might be characterized by the loss of AR in skeletal muscle cells." (PMID 38040692, 2023). "Since age-related muscle loss, or sarcopenia, is primarily characterized by a decrease in both the number and area of myofibers, it is possible that the age-related decline in androgen levels, which results in reduced AR expression in mesenchymal progenitors, contributes to these changes." (PMID 39292748, 2024). "The impact of the androgen–AR signaling transcriptional pathway on muscle function and sarcopenia has been outlined by several papers." (PMID 40181329, 2025). "Given the significant societal and economic impacts of sarcopenia, investigating the androgen/androgen receptor axis in skeletal muscle function is essential to enhance treatment efficacy and reduce healthcare costs." (PMID 40181329, 2025). "Various pharmaceutical strategies aimed at addressing primary sarcopenia have been explored, including selective androgen receptor modulators and the inhibition of activin receptors or myostatin through monoclonal antibodies." (PMID 40282842, 2025). "Decreased androgen receptor (AR) signaling in skeletal muscle leads to impaired muscle function and sarcopenia-like phenotype." (PMID 40151644, 2025). "Among these, LPCN 1148—a novel oral androgen receptor agonist—has shown significant efficacy in increasing lean body mass and reducing hepatic encephalopathy recurrence in cirrhotic men with sarcopenia." (PMID 40724988, 2025). "As androgens are essential for maintenance of muscle mass and strength and exogenous testosterone supply increases the muscle mass and leg strength in eugonadal young and aging men, the role of androgen/AR signaling in sarcopenia pathogenesis appears evident." (PMID 40181329, 2025). "In mCRPC patients receiving androgen receptor targeted therapy (ARAT), sarcopenia was significantly associated with severe treatment toxicity (aOR = 6.26) and an increased risk of first emergency department visit (aHR = 4.41)." (PMID 41377560, 2025). "Therapeutic interventions, such as testosterone and selective androgen receptor modulators, are common therapeutic treatments for patients with sarcopenia." (PMID 38272857, 2024). "Treatment for sarcopenia primarily includes testosterone, selective androgen receptor modulators, growth hormone analogs, etc.." (PMID 38771764, 2024). "Another promising method to reverse sarcopenia is the use of selective androgen receptor modulators (SARMs)." (PMID 38999435, 2024). "Pharmacological therapies for sarcopenia (testosterone, androgen receptor modulators, ghrelin agonists, myostatin inhibitors, ACE inhibitors) have been evaluated, but they are generally less effective than postulated (idem)." (PMID 33327483, 2020). "As such, therapeutic restoration of AR signaling—whether through hormonal replacement, SARMs, or downstream mimetics—holds promise for mitigating sarcopenia and age-related functional decline." (PMID 40724988, 2025). "Multimodal approaches, including nutritional support, physical therapy, and medications such as ibuprofen (Menac trial) and selective androgen receptor modulators, as well as ghrelin receptor activation with agonists, are recognized as foundational in managing sarcopenia." (PMID 38793093, 2024). "Future research may reveal promising pharmacological agents for treating sarcopenia, such as myostatin antagonists, selective androgen receptor modulators, and skeletal troponin activators." (PMID 37692743, 2023).
sarcopenia (continued). "Aggressive treatments for sarcopenia, such as selective androgen receptor modulators or angiotensin-converting enzyme inhibitors, might be considered." (PMID 35565877, 2022). "Therefore, analysis of the androgen receptor-mediated actions in skeletal muscle might provide new hints for a better understanding of sarcopenia pathogenesis." (PMID 38040692, 2023). "PE can also induce the expression of androgen receptor (AR), resulting in general anti-inflammatory effects through STAT3, counteracting STAT3-induced sarcopenia." (PMID 41011716, 2025). "In summary, SARMs represent a promising therapeutic approach for sarcopenia and SUI, as they selectively enhance pelvic muscle function through targeted AR activation." (PMID 41377560, 2025). "For sarcopenia, clinical trials reported different compounds, such as creatine, testosterone, bimagrumab, BCAA, androgen receptor modulators (SARM), losartan, citrulline, and IGF1 have been tested." (PMID 36010642, 2022). "Our findings of tissue-specific AR modulation by SARM-2f and of SARM-2f-mediated physical function improvements suggest that SARM-2f might represent an effective treatment for sarcopenia and cachexia." (PMID 29216311, 2017). "Hiroshige and collaborators found that among mCRPC patients treated with androgen receptor axis-targeted therapies, those with initial sarcopenia showed better PFS rates than their nonsarcopenic counterparts, marking sarcopenia as a potentially favorable prognostic factor in this context." (PMID 40421108, 2025). "As an alternative, selective androgen receptor modulators (SARMs) have been intensively investigated for possible application in diseases with muscular weakness, although to date no SARM compounds have been launched as therapeutic agents for sarcopenia or cachexia." (PMID 29216311, 2017). "Furthermore, in terms of pharmacological treatment, although there are currently no specific drugs for sarcopenia, certain medications, such as androgen, growth hormone and its analogs, and selective androgen receptor modulators may help improve muscle mass and function in specific situations." (PMID 40029915, 2025).
invasive breast carcinoma (29 papers, 2008 to 2025). A carcinoma that infiltrates the breast parenchyma. "AR expression levels were analyzed in 250 invasive breast cancers by immunohistochemistry and any association with the clinicopathological features was evaluated." (PMID 24403250, 2013). "In invasive breast carcinomas, AR-positive tumors have been associated with a low or intermediate histological grade (G1, G2)." (PMID 18507821, 2008). "Since AR is a favorable prognostic indicator, and its action in breast epithelium generally leads to inhibition of cell growth, loss of NcoA4 and/or AR in the presence of Her2/neu could represent more aggressive subtypes of invasive breast cancer." (PMID 22562579, 2012). "AREG is co-expressed with AR in invasive breast cancer, which is reported as one of the prognostic biomarkers and therapeutic targets in invasive breast cancer, particularly in ER-negative breast cancer (MCF-7)." (PMID 34490085, 2021). "Androgen receptor (AR) is an important transcriptional factor, which is frequently expressed in invasive breast cancer and correlates patients’ prognosis." (PMID 29423076, 2018). "Data from Nurse’s Health Study on women with invasive breast cancer suggest that a significant number of tumors were AR-positive as defined by immunohistochemistry." (PMID 28474005, 2017). "Immunohistochemical AR expression was assessed in 910 women with invasive breast cancer diagnosed 1991–2010, supplemented with clinicopathological information, vital status, and cause of death, with the last follow-up in December 2014 (median 10 years)." (PMID 28643022, 2017). "The present study investigated the expression of the AR by IHC and the relationship between AR expression and clinicopathological factors in primary invasive breast cancer." (PMID 24403250, 2013). "We considered that both AR and MMPs/TIMPs expression could be more important in the early phases of tumor progression, but less in primary invasive breast carcinomas." (PMID 18507821, 2008). "Likewise, AR is expressed in approximately 70% to 90% of invasive breast cancers, a frequency comparable with or higher than the one reported for ER (70–80%) and PgR (50–70%)." (PMID 18507821, 2008). "The second objective of this study was to assess the relationships between AR, FOXA1, and the other clinical and pathological features of feline invasive mammary carcinomas." (PMID 31888566, 2019). "The present study aims to examine the expression of AR, let-7a and CD44+/CD24-/low in invasive breast cancer tissue specimens." (PMID 29423076, 2018). "The results indicated that the expression levels of AR were higher in breast invasive carcinoma (BRCA) than in normal breast tissues, whereas the expression levels of ATF4 were lower in the former than in the latter." (PMID 35013318, 2022). "The androgen receptor (AR), a member of the nuclear steroid hormone receptor superfamily, is reported to be expressed in most invasive breast cancers when ER and PR are not detectable, as well as in 17–35% of established TNBC specimens." (PMID 29099049, 2017). "AR have also been detected in a significantly higher percentage of AR-positive ductal carcinomas "in situ" (DCIS) adjacent to invasive carcinomas of the breast than in pure DCIS lesions, suggesting that AR correlates with tumor invasiveness, at least in the early phases of tumor progression." (PMID 18507821, 2008). "A Yale study in the USA reported that of 400 invasive breast cancers cases, 12.5% were TNBC while 8% were quadruple negative breast cancer (QNBC) and 33% of TNBCs were AR positive." (PMID 36405944, 2022).
hypogonadism (27 papers, 2013 to 2025). A disorder characterized by decreased function of the gonads. "Exogenous AR agonists, however, are primarily used in clinical settings to treat diseases associated with low androgen receptor expression, such as hypogonadism." (PMID 37571268, 2023). "Herein, hypogonadism attenuated the RET induction of AR mRNA and protein levels possibly resulting in lower muscle T processing capacity due to lower T in the circulation." (PMID 35233984, 2022). "Selective Androgen Receptor Modulators (SARMs) work at the level of the androgen receptor and are potential alternatives to testosterone supplementation in patients with hypogonadism." (PMID 35233331, 2022). "Particularly, in the setting of hypogonadism, this result can be achieved through the knockout of the androgen receptor (AR)." (PMID 31817436, 2019). "Castration and the consequent hypogonadism or AR-antagonism therapy results in a significant reduction in Akt phosphorylation and an improved phenotype in the heart and kidneys of Fabry disease model mice." (PMID 28645930, 2017). "Conversely, in hypogonadism, testosterone-related effects will be strongly dependent on androgen levels, as testosterone binds to AR and will increase androgen effects until saturation of the receptors is reached." (PMID 28243253, 2016). "Symptoms include late-onset muscular weakness and atrophy, frequently accompanied by androgen insensitivity and hypogonadism, believed to be a result of AR protein aggregation resulting in apoptosis of affected cells." (PMID 23467468, 2013). "Contrawise, with growing evidence that lower, not higher, testosterone levels trigger the development of PCa and BPH through androgen receptor over-expression, a paradigm shift in altering the present approach to diagnosing and treating men with hypogonadism is advocated to improve men’s health." (PMID 37148486, 2023). "The future of hypogonadism therapy may lie in the development of selective androgen receptor modulators that allow the benefits of androgens whilst minimizing unwanted side effects." (PMID 28149506, 2017). "The general role of androgens in bone metabolism, loss of bone mass in cases of hypogonadism, and reduction in bone turnover with testosterone treatment all lead to predictions for a decrease in bone mass density (BMD) and increase in osteoporosis (femoral neck BMD <0.56 g/cm2) with longer AR CAGn." (PMID 23467468, 2013). "2‐Chloro‐4‐[[(1R,2R)‐2‐hydroxy‐2‐methyl‐cyclopentyl]amino]‐3‐methyl‐benzonitrile (LY305) is a transdermal selective androgen receptor modulator (SARM) that has been under development as a potential therapeutic for conditions involving muscle wasting, osteoporosis, or hypogonadism." (PMID 40814730, 2025). "Although rare, male patients with X-ALD may present with hypogonadism with normal or reduced testosterone and elevated luteinizing hormone (LH) levels, likely due to VLCFA toxicity on testicular Sertoli and Leydig cells and potential androgen receptor resistance." (PMID 41480351, 2025).